Y_RNA (Y RNA )
Gene: Miscellaneous RNA gene on chromosome 12 (62,935,701 to 62,935,802, forward strand). Ensembl gene ENSG00000252660.
Homologues: Orthologues: chimpanzee Y_RNA (100% identical), macaque Y_RNA (96% identical), dog Y_RNA (88% identical). Paralogues in human: Y_RNA (92% identical), RNY3 (91% identical), Y_RNA (91% identical), RNY3P1 (90% identical), Y_RNA (90% identical), Y_RNA (89% identical), Y_RNA (88% identical), RNY3P11 (87% identical), Y_RNA (87% identical), RNY3P14 (86% identical), RNY3P16 (86% identical), Y_RNA (86% identical), and 96 more.